KRTAP9-4 (keratin associated protein 9-4)
Description:
In the hair cortex, hair keratin intermediate filaments are embedded in an interfilamentous matrix, consisting of hair keratin-associated proteins (KRTAP), which are essential for the formation of a rigid and resistant hair shaft through their extensive disulfide bond cross-linking with abundant cysteine residues of hair keratins. The matrix proteins include the high-sulfur and high-glycine-tyrosine keratins.
Synonyms: KAP9.4; KRTAP9.4
Tractability: No criterion of Open Targets' tractability assessment is met for any kind of drug.
Gene: Protein-coding gene on chromosome 17 (41,249,687 to 41,250,653, forward strand). Ensembl gene ENSG00000241595.
Pathways (Reactome):
Developmental Biology: Keratinization
Gene Ontology:
Molecular function: protein binding
Cellular component: cytosol; keratin filament
Genetic constraint (gnomAD): Loss-of-function variants: 8 observed, 12.35 expected, observed/expected ratio (o/e) 0.65, 90% interval 0.38 to 1.17. The upper end of that interval is the gene's LOEUF score, 1.17, which puts it in group 5 of 6, group 1 being the genes least tolerant of losing a copy. Missense variants: 188 observed, 182.07 expected, observed/expected ratio (o/e) 1.03, 90% interval 0.92 to 1.16. Synonymous variants: 81 observed, 64.18 expected, observed/expected ratio (o/e) 1.26, 90% interval 1.05 to 1.52.
Homologues: Paralogues in human: KRTAP9-2 (96% identical), KRTAP9-8 (91% identical), KRTAP9-9 (90% identical), KRTAP9-3 (90% identical), KRTAP9-7 (87% identical), KRTAP9-6 (85% identical), KRTAP9-1 (79% identical), KRTAP4-12 (51% identical), KRTAP4-9 (50% identical), KRTAP4-6 (49% identical), KRTAP4-11 (47% identical), KRTAP4-5 (45% identical), and 35 more.